CDO1 (cysteine dioxygenase type 1)
Diseases named in the same sentence as CDO1 in open-access papers (continued):
Sharing a sentence is not in itself a finding about the gene and the disease.
adenoma (3 papers, 2014 to 2019). A neoplasm arising from the epithelium. "As a result, utilization of CDO1 methylation abnormality can be expected as a biomarker for detection from adenoma to SBC." (PMID 30677088, 2019). "An analysis of the clinicopathological background factors in adenoma showed that CDO1 TaqMeth V tended to increase in parallel with age (p = 0.006, R2 = 0.039)." (PMID 29746493, 2018). "In other words, these observations suggest that methylation of SEPT9 is superior as a marker of cancer, and methylation of CDO1 can be detected with high frequency in some types of adenoma." (PMID 29746493, 2018). "Our study suggested that aberrant methylation of CDO1 is involved in the development and growth of adenoma, progression of atypia, oncogenic transformation, invasion, and metastasis." (PMID 29746493, 2018). "Furthermore, the fact that TaqMeth V also differed significantly between low-grade adenoma and high-grade adenoma suggested that CDO1 methylation contributes to the growth of adenoma and an increased grade of atypia." (PMID 29746493, 2018). "When excised samples were used, methylation abnormalities of CDO1 could be distinguished from normal mucosa at the stage of adenoma as well as cancer tissue." (PMID 29746493, 2018). "The cut-off CDO1 TaqMeth V that could distinguish low-grade adenoma from NAM was determined with ROC curve analysis." (PMID 29746493, 2018). "As a result, the area under the curve by CDO1 promoter methylation was 0.96, 0.80, and 0.67 to discriminate cancer from NAM, low-grade adenoma from NAM, and low-grade adenoma from high-grade adenoma, respectively." (PMID 29746493, 2018). "Due to the low sensitivity for the assay (20%) of plasma methylated CDO1, the utility of the test for population screening for CRC will require improved sensitivity for detection of early cancers and advanced adenomas." (PMID 25469504, 2014). "The combination of CDO1 and SEPT9 methylation could be a very effective tool for the detection of CRC or adenoma." (PMID 29746493, 2018). "However, because CDO1 methylation was significantly higher in cancer with liver metastasis than in high-grade adenoma and cancer with no liver metastasis, CDO1 methylation likely contributes to tumor cell migration and invasion." (PMID 29746493, 2018).
Cirrhosis (3 papers, 2014 to 2024). A chronic disorder of the liver in which liver tissue becomes scarred and is partially replaced by regenerative nodules and fibrotic tissue resulting in loss of liver function. "In the present study, we focused on the effect of TGF-β, a key mediator of fibrogenesis in the development of cirrhosis, and demonstrated that Cdo1 gene transcription is suppressed by TGF-β." (PMID 24553827, 2014). "We corroborated the expression levels of BHMT and CDO1 in various HCC cohorts and observed a marked suppression in HCC tumors compared to normal and cirrhosis samples across all independent cohorts examined." (PMID 39516467, 2024). "Thus, the observation suggests that the suppression of Cdo1 gene by TGF-β and subsequent decline of taurine level may be important for the development of cirrhosis." (PMID 24553827, 2014).
colon cancer (3 papers, 2012 to 2020). "Taken together, these results indicate that CDO1 suppresses the in vitro and in vivo tumorigenicity of human colon cancer cells." (PMID 23028699, 2012). "Immunohistochemical analysis of CDO1 in colon cancer tissue microarray." (PMID 23028699, 2012). "Thus, CDO1 can suppress cell growth and anchorage independence of human colon cancer cells." (PMID 23028699, 2012). "Mossman and Scott demonstrated in 2 colon cancer cell lines (HCT116 and SW480), treatment with 5-Aza-dC was able to induce gene expression of CDO1, but this expression was not complete and could be reverted after a few days." (PMID 23028699, 2012).
esophageal cancer (3 papers, 2012 to 2019). A primary or metastatic malignant neoplasm involving the esophagus. "Immunohistochemical analysis of CDO1 in esophageal cancer tissue microarray with normal tissue controls (ES804)." (PMID 23028699, 2012). "In addition, in esophageal cancer cell lines, forced expression of CDO1 reduces tumor cell proliferation, cell migration, invasion, and colony formation." (PMID 29746493, 2018).
glioblastoma (3 papers, 2014 to 2025). The most malignant astrocytic tumor (WHO grade IV). "High CBS and CDO1 expression, as well as high levels of sulfane sulfur in T98G glioblastoma cells, suggests that sulfur metabolism is a critical determinant of tumor redox balance." (PMID 41154707, 2025). "In contrast with these recent studies suggesting attenuating this pathway contributed toward tumorigenesis, our findings demonstrate activation of the CDO1/CSA axis is a common metabolic phenotype glioblastoma." (PMID 24351290, 2014). "Tumors with CSA levels ≥1 (representing the median value) demonstrated a significant increase in CDO1 expression, suggesting intratumoral concordance between CSA levels and CDO1 expression and further supports cysteine catabolism along this parallel pathway is a relevant event in glioblastoma." (PMID 24351290, 2014). "Studies performed in vivo abrogating the CDO1/CSA axis using a lentiviral-mediated short hairpin RNA approach resulted in significant tumor growth inhibition in a glioblastoma mouse model, supporting the potential for this metabolic pathway to serve as a therapeutic target." (PMID 24351290, 2014). "Although intragrade heterogeneity of CDO1 expression was identified in glioblastoma, with a quartile of tumors demonstrating low CDO1 expression, high expression of CDO1 (>40%) was observed exclusively in grade 4 tumors, a pattern that was present in a quartile of tumors." (PMID 24351290, 2014). "Interestingly, the inhibition of CDO1 attenuates glioblastoma growth in vivo." (PMID 41154707, 2025). "Therefore, it is possible that modulation of the activity of both CBS and CDO1 may affect the antioxidant potential and survival of T98G glioblastoma cells, which we intend to verify in further studies." (PMID 41154707, 2025). "We first evaluated CDO1 expression, the enzyme involved in CSA synthesis, in a panel of glioblastoma lines." (PMID 24351290, 2014). "In this report, we describe the discovery of cysteine catabolism through CDO1 expression and biosynthesis of the metabolite CSA as a novel metabolic pathway in glioblastoma." (PMID 24351290, 2014).
lymph node metastasis (3 papers, 2016 to 2019). "BC patients with aggressive lymph node metastasis more frequently exhibited promoter DNA hypermethylation of CDO1 than those with modest lymph node metastasis (p = 0.01)." (PMID 26785325, 2016). "Reflected on this finding with regard to lymph node metastasis, CDO1 promoter DNA hypermethylation is also significantly associated with stage (p = 0.02)." (PMID 26785325, 2016). "The other clinicopathological factors, such as preoperative serum values of CA19-9, lymph node metastasis, distant metastasis, and lymphatic permeation, were not significantly related to CDO1 TaqMeth values based on analysis of variance (ANOVA)." (PMID 29161283, 2017).
metastasis (3 papers, 2017 to 2020). The spread or migration of cancer cells from one part of the body (where they first appeared) to another. "Furthermore, primary CRC cancers with liver metastasis harbored significantly higher methylation of CDO1 than those without liver metastasis (p = 0.02)." (PMID 29746493, 2018).
Obesity (3 papers, 2022 to 2025). Accumulation of substantial excess body fat. "Cysteine dioxygenase 1 (Cdo1), essential for taurine synthesis from cysteine, has been linked to lipolytic capacity in adipose tissue, with Cdo1 knockout mice displaying reduced free fatty acids and increased susceptibility to obesity." (PMID 39940040, 2025). "Notably, adipose tissue specific loss- and gain-of function experiment in mice showed that Cdo1 ameliorated diet-induced obesity and related metabolic disorders by promoting lipolysis." (PMID 38110408, 2023). "Our previous research showed that adipose-specific knockout of Cdo1 in mice impairs energy expenditure, cold tolerance and lipolysis, exacerbates diet-induced obesity and decreases adipose expression of the key lipolytic genes." (PMID 38110408, 2023). "Adipose tissues play a central role in the pathogenesis of obesity and the expression changes and role of CDO1 in the subcutaneous (SAT) and visceral (VAT) white adipose tissue and the translational significance thereof in humans with obesity remain unclear." (PMID 36335668, 2022).
esophageal squamous cell carcinoma (2 papers, 2018 to 2020). Esophageal squamous cell carcinoma (ESCC) is a type of esophageal carcinoma (EC) that can affect any part of the esophagus, but is usually located in the upper or middle third. "Such prognostic associations with CDO1 methylation have been previously reported in various histological types of cancers such as renal clear-cell carcinoma, breast adenocarcinoma, and esophageal squamous cell carcinoma." (PMID 29746493, 2018).
leukaemia (2 papers, 2025). "Inhibition of either CDO1-driven stromal taurine synthesis or TAUT-mediated uptake significantly impairs leukemia progression and improves survival in preclinical acute myeloid leukemia models." (PMID 41003014, 2025). "To test whether CDO1 is expressed in the human leukaemia TME, we performed an scRNA-seq analysis of CD45− stromal cells from three myelodysplastic syndrome (MDS) and AML bone marrow aspirates." (PMID 40369079, 2025). "While the leukaemia TME did not express enzymes required for β-alanine synthesis (Gadl1 and Cndp1), those needed for taurine biosynthesis were expressed in osteo-associated cells (Cdo1 and Csad)." (PMID 40369079, 2025).
liver cancer (2 papers, 2019 to 2021). An epithelial or non-epithelial malignant neoplasm that arises from the liver. "Only HepG2, a liver cancer cell line expressed CDO1 gene, and suppression of CDO1 gene by RNA interference resulted in invasive capacity as described by Brait M." (PMID 30934021, 2019).
lung adenocarcinoma (2 papers, 2019 to 2022). A carcinoma that arises from the lung and is characterized by the presence of malignant glandular epithelial cells. "CDO1 mRNA expression was significantly lower in lung adenocarcinoma samples compared to normal lung, which was associated with CDO1 promoter methylation and poor prognosis." (PMID 31107239, 2019). "The resulting 245 differentially methylated regions were enriched for lung adenocarcinoma-specific 5-mC patterns in TCGA data and indicated transcriptional repression of several genes described to be silenced in NSCLC (e.g., PCDH10, TBX2, CDO1, and HOXA9)." (PMID 36461127, 2022). "(a) CDO1 mRNA expression of normal lung (Normal) or or KEAP1 wild-type (WT) and mutant (MUT) lung adenocarcinoma patient tumor samples." (PMID 31107239, 2019). "(b) Methylation of the CDO1 promoter in samples from normal lung (Normal) or KEAP1 wild-type (WT) and mutant (MUT) lung adenocarcinoma patient tumor samples." (PMID 31107239, 2019).
ovarian carcinoma (2 papers, 2024). A malignant neoplasm originating from the surface ovarian epithelium. "Three methylation markers are significantly elevated in full void urine of ovarian cancer patients as compared to healthy controls (C2CD4D, P = 0.008; CDO1, P = 0.022; MAL, P = 0.008), of which two are also discriminatory in cervical scrapes (C2CD4D, P = 0.001; CDO1, P = 0.004)." (PMID 38755429, 2024).
renal clear-cell cancer (2 papers, 2017 to 2018). "Promoter DNA of the CDO1 gene has been reported to be frequently methylated in various cancers, including breast, esophagus, lung, bladder, gastric, colorectal, biliary tract, hepatocyte, renal clear-cell cancer, and testicular germ cell cancers." (PMID 29161283, 2017).
small bowel cancer (2 papers, 2019 to 2022). "The methylation status of CDO1 was specifically high in small bowel cancer (SBC), which indicates it is a biomarker of SBC." (PMID 36164519, 2022).
Alzheimer disease (1 paper, 2012). A progressive, neurodegenerative disease characterized by loss of function and death of nerve cells in several areas of the brain leading to loss of cognitive function such as memory and language. "Cysteine regulates CDO1 turnover through Ubiqutin-26S proteasome-mediated degradation, and a high level of cysteine is cytotoxic and can cause rheumatoid arthritis, Parkinson’s disease, Alzheimer’s disease, increased risk of cardiovascular disease and adverse pregnancy outcomes." (PMID 23028699, 2012).
breast benign diseases (1 paper, 2023). "The PMR of CDO1 promoter in BC patients (7.46% ± 15.38) was significantly higher than that in the normal people (.19% ± .83, p < .0001) and patients with breast benign diseases (.04% ± .15, p < .0001)." (PMID 37740473, 2023).
colorectal tumors (1 paper, 2016). "CDO1 plays a tumor suppressive role in human carcinogenesis and is frequently inactivated by promoter methylation in breast, esophagus, lung, bladder, gastric and colorectal tumors." (PMID 27355345, 2016).
cutaneous T-cell lymphoma (1 paper, 2010). "Recently, over-expression of CDO1 was described for the Sézary syndrome, an aggressive cutaneous T-cell lymphoma." (PMID 20515469, 2010).
ductal carcinoma in situ (1 paper, 2010). "Interestingly, repression of Cdo1 expression was identified to be associated with the malignant transition from mammary intraepithelial neoplasia to tumors in an engineered mouse-based model of ductal carcinoma in situ." (PMID 20515469, 2010).
Fanconi anemia (1 paper, 2021). Fanconi anemia (FA) is a hereditary DNA repair disorder characterized by progressive pancytopenia with bone marrow failure, variable congenital malformations and predisposition to develop hematological or solid tumors. "Among them, cysteine dioxygenase 1 (CDO1), toll-like receptor 4 (TLR4), and dual oxidase 1 (DUOX1) were downregulated in tumors and played a protective role, while Fanconi anemia complementation group D2 (FANCD2) and others were with high expression in tumors and were risk factors for prognosis." (PMID 34820377, 2021).
fatty liver (1 paper, 2023). "In our study, it was found that the knockdown of AMPK blunted the role of Cdo1 in improving hepatic steatosis." (PMID 38110408, 2023). "Liver-derived Cdo1 plays an important role in exercise-mediated alleviation of hepatic steatosis in mice." (PMID 38110408, 2023). "We further evaluated the role of Cdo1 in hepatic steatosis by treating primary hepatocytes from Cdo1flox/flox mice with oleic acid (OA) and palmitic acid (PA)." (PMID 38110408, 2023). "Then, gain-of-function experiments were performed to investigate whether Cdo1 overexpression could attenuate hepatic steatosis in vitro." (PMID 38110408, 2023). "Thus, hepatic Cdo1 could promote FAO and mitochondrial biogenesis to inhibit hepatic steatosis, in which AMPK signaling could be involved." (PMID 38110408, 2023).
gallbladder disease (1 paper, 2017). "In this study, we investigated for the first time the clinicopathological and prognostic relevance of promoter DNA methylation of the CDO1 gene in primary GBC in comparison with gallbladder disease." (PMID 29161283, 2017).
hepatic diseases (1 paper, 2014). "Furthermore, our observation that BCAA promotes Cdo1 expression suggests that BCAA may be therapeutically useful to improve hepatic taurine metabolism and further suppress dysfunctions associated with low level of taurine in hepatic diseases." (PMID 24553827, 2014). "Finally, we show that the decreased Cdo1 expression can be rescued by BCAA supplementation, which is often used as a treatment for hepatic disease patients." (PMID 24553827, 2014).
leiomyoma (1 paper, 2019). A well-circumscribed benign smooth muscle neoplasm characterized by the presence of spindle cells with cigar-shaped nuclei, interlacing fascicles, and a whorled pattern. "Malignant lymphoma, GIST, and leiomyoma cannot be disregarded when considering small bowel tumors and therefore, methylation abnormality of CDO1 was also investigated in these tumors." (PMID 30677088, 2019).
leiomyosarcoma (1 paper, 2019). An uncommon, aggressive malignant smooth muscle neoplasm, usually occurring in post-menopausal women. "Although high CDO1 methylation was observed in malignant lymphoma as well as in adenocarcinoma, CDO1 methylation was extremely low in leiomyosarcoma and in GIST that is characterized by spindle shaped cells." (PMID 30677088, 2019). "Among small bowel tumors, CDO1 methylation in SBC was higher in order of malignant lymphoma, cancer, and leiomyosarcoma/GIST (p = 0.002) by ANOVA." (PMID 30677088, 2019).
lung squamous cell carcinoma (1 paper, 2017). "A recent genome-wide analysis of DNA methylation and gene expression changes in lung squamous cell carcinoma identified several methylation-driven genes, including CCDC37, CYTL1, CDO1, SLIT2, LMO3 and SERPINB538." (PMID 28198450, 2017).
malignant lymphoma (1 paper, 2019). "In the comparison of TaqMeth V among tumors including SBC, malignant lymphoma showed high CDO1 methylation along with SBC, whereas CDO1 methylation in GIST was significantly lower than that of these two tumors (p = 0.002)." (PMID 30677088, 2019).
osteoarthritis (1 paper, 2024). A noninflammatory degenerative joint disease occurring chiefly in older persons, characterized by degeneration of the articular cartilage, hypertrophy of bone at the margins and changes in the synovial membrane. "Moreover, curcumin may have therapeutic effects on osteoarthritis by interacting with the CTH, CBS, CDO1, and PSAT1 proteins involved in cysteine and methionine metabolism." (PMID 37938371, 2024).
osteoporosis (1 paper, 2016). A condition of reduced bone mass, with decreased cortical thickness and a decrease in the number and size of the trabeculae of cancellous bone (but normal chemical composition), resulting in increased fracture incidence. "Our results indicate that Cdo1 may contribute to the development of osteoporosis." (PMID 26763277, 2016).
pancreatic (1 paper, 2021). "Further analyses on a large patient cohort, examining the methylation status of CDO1 in patients with pancreatitis, pseudocysts and a variety of pancreatic cystic lesions would be required to further validate this marker." (PMID 33673153, 2021).
pancreatic ductal adenocarcinoma (1 paper, 2021). An infiltrating adenocarcinoma that arises from the epithelial cells of the pancreas. "In pancreatic ductal adenocarcinoma, the hypermethylation of the CDO1 promoter is highly specific in tumor tissues." (PMID 34246261, 2021).
Pleural effusion (1 paper, 2021). The presence of an excessive amount of fluid in the pleural cavity. "Interestingly, Ooki and colleagues, determined the clinical utility of a set of six genes, including CDO1, HOXA9, AJAP1, PTGDR, UNCX, and MARCH11, for predicting LC diagnosis not only in serum samples but also in pleural effusions and ascites." (PMID 33937034, 2021).
preeclampsia (1 paper, 2022). Preeclampsia is a hypertensive disorder of pregnancy that is characterized by new-onset hypertension with proteinuria presenting after 20 weeks of gestation, and depending on mild or severe forms may initially present with severe headache, visual disturbances, and hyperreflexia. "Regarding the potential of markers for discriminating preeclampsia patients from normal pregnant women, the ROC analysis revealed that the AUC values of the NQO1, SRXN1, CDO1, EGFR, FBXW7, and JUN are 0.803, 0.748, 0.708, 0.703, 0.665, and 0.681, respectively." (PMID 36061193, 2022).
renal carcinoma (1 paper, 2020). A carcinoma arising from the epithelium of the renal parenchyma or the renal pelvis. "In recent years, with the deepening of epigenetic research, the epigenetic regulatory mechanisms of renal cancer, especially DNA methylation, are often used to predict the survival time of renal cancer, including DAB2IP, RCVRN, CRHBP, AR, and CDO1." (PMID 32733620, 2020).